HMGB1 (high mobility group box 1)
Diseases named in the same sentence as HMGB1 in open-access papers (continued):
Sharing a sentence is not in itself a finding about the gene and the disease.
cancer (continued). "Overexpression of HMGB1 in cancer cells and elevated serum levels in GC have been demonstrated in several studies." (PMID 29728635, 2018). "NET-released high mobility group box 1 (HMGB1) augments cancer cell adhesion, proliferation, and migratory capabilities in vitro in a toll-like receptor 9 (TLR9)-dependent manner." (PMID 30200242, 2018). "Soluble RAGE, the HMGB1 antibody, and other agents, such as glycyrrhizin and quercetin that target HMGB1 showed a promising prospect for anti-cancer therapy." (PMID 29728635, 2018). "Extracellular HMGB1 is released by both cancer and infiltrating immune cells within the inflammatory TME." (PMID 30643519, 2018). "To further confirm HMGB1 release from the dying cancer cells (required to promote cancer cell invasion), we performed HMGB1 stable knockdown in Panc-1 feeder cells (HMGB1-/-Panc-1) using shRNA technology and confirmed the silencing efficiency by Western blot." (PMID 29615080, 2018). "Of note, either knockdown Zeb1 or inhibit the phosphorylation of Akt activity, HMGB1 induced the migratory capacity of cancer cells was abrogated." (PMID 29615080, 2018). "The role of HMGB1 (a chromatin binding protein) in processes relevant to cancer cell survival include autophagy, genome stability, angiogenesis and invasion and metastasis." (PMID 29254158, 2017). "The clinical correlation of circulating HMGB1 levels with various diseases including cancer has been reported." (PMID 28536706, 2017). "The strong decrease of cellular HMGB1 is in agreement with literature showing that cancer cells secrete and overexpress HMGB1 by stimulation of growth factors, cytokines, and cellular stress." (PMID 28951871, 2017). "HMGB1 has been suggested to normally have anti-apoptotic effects in cancers, but paradoxical roles in promoting apoptosis were identified in cardiomyocytes and mouse embryonic fibroblasts." (PMID 29246127, 2017). "NK cells invoke this strategy by employing HMGB1 protein, which specifically targets glycolysis in cancer cells and opens up new perspectives for cancer immunotherapy." (PMID 29190907, 2017). "HMGB1, known primarily as a regulator of autophagy, is expressed in various normal cells and has also been confirmed to be involved in cancer development by interfering with several signaling pathways." (PMID 29296182, 2017). "The present study revealed that miR-410-3p attenuated gemcitabine resistance in PDAC cancer cells by targeting the 3′UTR of HMGB1." (PMID 29296182, 2017). "We show that antagonizing HMGB1 prevents the adhesion and colonization of cancer cells in the lungs through the reduction of their adhesion and cell–cell interaction both in vitro and in vivo." (PMID 28415753, 2017). "Numerous strategies have being employed to restrain the activity and release of HMGB1 in anti-cancer therapeutics." (PMID 28969092, 2017). "This review is focused on the current knowledge of HMGB1 biological features, especially in relation to the development of cancer and its potential therapeutic values." (PMID 28969092, 2017). "Currently, several strategies have been proposed to inhibit HMGB1 expression, activity and release in a direct or indirect manner for treatment of cancer as well as various inflammatory diseases." (PMID 28969092, 2017). "High-mobility group box 1 (HMGB1) has been found to mediate autophagy during chemotherapy in several cancers." (PMID 29069735, 2017). "It is demonstrated that the HMGB1-RAGE signaling axis contributes to cell proliferation and metastasis by inducing nuclear factor κB (NF-κB) activation, revealing HMGB1-RAGE as a potential target for therapeutic intervention in cancer." (PMID 28969092, 2017). "Activation of the HMGB1 signaling pathway leads to downstream upregulation of RAGE expression, which establishes an autocrine loop of activation that, in turn, sustains HMGB1 secretion and supports the survival of HMGB1-dependent cancers." (PMID 28186988, 2017).
cancer (continued). "Studies in cancer cells show that HMGB1 is a regulator of the balance between autophagy and apoptosis." (PMID 29033853, 2017). "As a nuclear protein, the expression and translocation of HMGB1 plays a critical role in the response to chemotherapy in cancer." (PMID 29296182, 2017). "Ethyl pyruvate (EP), the ethyl ester of pyruvic acid, has been shown to be an effective HMGB1 inhibitor in inflammation-related diseases and several cancers." (PMID 28186988, 2017). "Due to its versatile role in cancer, HMGB1 has been proposed as a potential biomarker of survival and a target for cancer therapy." (PMID 29246127, 2017). "RT can also induce immunogenic cancer cell stress or death and promote the transfer of calreticulin to cancer cell plasma membranes and the release of ATP and HMGB1." (PMID 28687760, 2017). "Because HMGB1 affects multiple biological events in HCC and contributes to drug resistance in certain cancers, this study aims to explore the role of HMGB1 in sorafenib resistance in HCC using the HepG2 cell line and murine models." (PMID 29246127, 2017). "Previous studies have shown that HMGB1 overexpression is a common and widespread phenomenon in numerous cancers and is involved in cancer progression and malignant behaviors." (PMID 29069735, 2017). "Knockdown of HMGB1 using antisense oligodeoxynucleic acid technology inhibits cancer cell growth and metastasis." (PMID 28969092, 2017). "Previously reports suggested that HMGB1 mediates autophagy induced by chemotherapeutics in other cancer." (PMID 29069735, 2017). "Due to its critical role in cancer, in the last few years, several efforts have been made to identify both natural and synthetic compounds able to inhibit HMGB1 activities." (PMID 28186988, 2017). "Other results identified that HMGB1 can modulate cancer cell biology and epithelial-mesenchymal transition." (PMID 27829233, 2017). "Circulating HMGB1 levels have been clinically and pathologically correlated with various diseases, including cancer." (PMID 28536706, 2017). "Increasing clinical evidence indicates that extracellular HMGB1 contributes to inflammatory disorders and cancer development." (PMID 28348451, 2017). "Carbon ion radiation increased the levels of high mobility group box 1 (HMGB1) in the culture supernatants of different human cancer cell lines." (PMID 28275377, 2017). "The majority of carcinoma samples (32/51) showed a higher expression of HMGB1, while the rest (19/51) had a lower HMGB1 level." (PMID 29069735, 2017). "Cancer cells can acquire resistance to HMGB1 by increasing glycolysis using the dimeric form of PKM2, and employing glutaminolysis." (PMID 26948869, 2016). "Taken together, these studies confirm that chemotherapeutic treatment of cancer patients leads to changes in the blood levels of HMGB1." (PMID 27457217, 2016). "The TLR4 or RAGE interaction with HMGB1 released from cancer cells engages downstream the PI3K and MAPK pathways to signal the myofibroblasts to proliferate, migrate and invade." (PMID 26979829, 2016). "Recently, we described that HMGB1 induces a distinct form of necrotic cell death in cancer cells which differed from the classical cell death entities known so far9." (PMID 26948869, 2016). "It is clear that HMGB1 has a broad repertoire of immunological functions and is involved in various pathways of immunity, inflammation and cancer progression, therefore also the induction by infection with PUUV, DOBV or CCHFV can influence different pathways." (PMID 27348219, 2016). "The biological functions of HMGB1 are diverse in normal cells and during the start and progression of cancer." (PMID 26682011, 2016). "Despite the extensive investigations of HMGB1 expression in tissues and its corresponding serological activity on cancer evolution, there are a few studies focusing on the effect of the SNPs in HMGB1 gene on cancer prognosis or treatment response so far." (PMID 27116470, 2016).
cancer (continued). "In this article, we conducted a meta-analysis to evaluate HMGB1 mRNA and protein expression levels in tissue or serum from patients with cancer." (PMID 27391431, 2016). "In 16 included studies, multivariate analysis with the Cox's proportional hazards model was also performed to demonstrate that HMGB1 was an independent prognostic factor for patients with cancer." (PMID 27391431, 2016). "Preliminary data from our laboratory suggest that HMGB1 also has the potential to kill anoxic cancer cells." (PMID 27652323, 2016). "The results of our work show that the nuclear protein HMGB1 is released from glucose-deprived cancer cells." (PMID 26979829, 2016). "A recent meta-analysis also showed higher expression of C-X-C chemokine receptor 4 (CXCR4), another HMGB1′s receptor, indicated poorer prognosis in various types of cancer." (PMID 27391431, 2016). "In recent years, HMGB1 is also recognized as Inflammatory factors, which can be actively secreted from immune cells or cancer cells, or can be passively released from necrotic or damaged cells." (PMID 27100831, 2016). "When injected into established cancers, LTX-315 caused a transiently hemorrhagic focal necrosis that was accompanied by massive release of HMGB1 (from close-to-all cancer cells), as well as caspase-3 activation in a fraction of the cells." (PMID 26962684, 2016). "As an important alarm, the prognostic role of high mobility group box 1 (HMGB1) in cancer remains controversial." (PMID 27391431, 2016). "At the same time, some studies have demonstrated that HMGB1 is constitutively expressed in the nucleus and perinuclear organelles of cancer cells with the active nucleo-cytoplasmic shuttling of HMGB1 existing." (PMID 27391431, 2016). "Recent studies have shown that the HMGB1 gene is highly expressed in various cancers, showing oncogene-like biomarkers of these cancers." (PMID 26840258, 2016). "Steroid hormones that induce HMGB1 overexpression sensitize cancer cells to cisplatin and carboplatin." (PMID 26682011, 2016). "Release of ATP, heat shock proteins and high-mobility group box 1 (HMGB1) by dying cancer cells help in recruiting and activating DCs through toll-like receptor signaling pathways." (PMID 31093338, 2016). "Compelling evidences have suggested that high mobility group box-1 (HMGB1) gene plays a crucial role in cancer development and progression." (PMID 27116470, 2016). "The expression levels of HMGB1 in NSCLC tissues were significantly higher than in healthy non-cancer control tissues." (PMID 26840258, 2016). "Systematic literature searches of PubMed, Embase and Web of Science databases were performed for eligible studies of HMGB1 as prognostic factor in cancer." (PMID 27391431, 2016). "Here we show that natural killer cell-derived HMGB1 directly eliminates cancer cells by triggering metabolic cell death." (PMID 26948869, 2016). "HMGB1 overexpression has been observed in the cells of some cancers such as breast cancer, colon cancer, gastrointestinal stromal tumors, and liver cancer." (PMID 27836008, 2016). "In summary, HMGB1 overexpression is associated with poorer prognosis in terms of OS and PFS in patients with various types of cancer, suggesting that it is a prognostic factor and potential biomarker for survival in cancer." (PMID 27391431, 2016). "In fact, numerous studies have previously demonstrated the over-expression of HMGB1 in many types of cancer, including GC." (PMID 27116470, 2016). "The cytoplasmic HMGB1 was found to bind with a number of molecules related to cancer progression, including factors involvement in cell cycle progression, cell proliferation, and anti-apoptosis." (PMID 26499944, 2016).
cancer (continued). "In cancer cells, exogenous HMGB1 enters the mitochondria, which is followed by the formation of giant mitochondria independently of HMGB1 receptors such as TLR4 or RAGE." (PMID 27147971, 2016). "We show that natural killer (NK) cells pursue this strategy by employing high mobility group box 1 (HMGB1) protein—a well-known proinflammatory cytokine—to specifically target glycolysis in cancer cells." (PMID 27652323, 2016). "All of these characteristics appoint HMGB1 as an important target in the treatment of multiple human diseases, including immune disorders, infectious diseases, and cancer." (PMID 27634894, 2016). "The release of HMGB1 from cancer cells under low-glucose conditions and its subsequent interaction with myofibroblasts have not been previously reported." (PMID 26979829, 2016). "Now we have known that HMGB1 was involved in transcription regulation of many cancer genes, including E-selectin, TNF-α, BRCA1 and insulin receptor." (PMID 27391431, 2016). "Overexpression of RAGE and HMGB1 has been observed during cancer progression, invasion, and metastasis." (PMID 26682011, 2016). "Necrotic cells, particularly those derived from cancer tissues, passively release HMGB1, mediating local inflammation and cancer development." (PMID 27836008, 2016). "As increasing evidence indicates, HMGB1 contributes to inflammation disorders and cancer development, and it is important that HMGB1 is considered as a novel therapeutic target." (PMID 27563308, 2016). "HMGB1-mediated RAGE activation participates in various pathological conditions including cancer, sepsis, diabetes and Alzheimer’s disease." (PMID 27026438, 2016). "We also propose the possible mechanisms underlying PPAR involvement in inflammatory disorders and discuss the future therapeutic value of PPAR ligands targeting HMGB1 molecule for cancer prevention and treatment." (PMID 27563308, 2016). "The pooled estimate showed a significant shorter PFS in cancer patients with HMGB1 overexpression (HR: 2.26; 95% CI, 1.65-3.10)." (PMID 27391431, 2016). "The experiments in our previous work showed that HMGB1-mediated killing of cancer cells by NK cells (with up to 160 nM HMGB1) is restricted to normoxic cancer cells that still rely on aerobic respiration." (PMID 27652323, 2016). "Twenty relevant articles involving 2651 patients were included in this meta-analysis; the HMGB1 expression in NSCLC tissues was significantly higher than that in the healthy non-cancer control tissues." (PMID 26840258, 2016). "We report that the microenvironmental condition of glucose deprivation is responsible for the active release of HMGB1 from various types of cancer cell lines (HT-29, MCF-7 and A549) under normoxic conditions." (PMID 26979829, 2016). "Both HMGB1 partly (HCT116) and highly resistant (HT29) cancer cells compensated the HMGB1-caused decline of ATP production efficiently by glycolysis, whereas SW480 cells showed a strong decline of ATP production of ∼50%." (PMID 26948869, 2016). "Nonetheless, HMGB1 has a broad repertoire of immunological functions and is involved in different pathways of immunity, inflammation and cancer progression." (PMID 27348219, 2016). "Recent findings have revealed that HMGB1 dysfunction contributes to cancer initiation and development." (PMID 25772485, 2015). "Recently, apoptotic cancer cells were also shown to release HMGB1 at some points in the irrespective execution phases." (PMID 26625309, 2015). "Some anticancer therapeutics efficiently kill cancer cells (hence promoting the release of HMGB1) and stimulate the secretion of both ATP and type I IFNs, but selectively fail to promote CALR exposure." (PMID 25964783, 2015). "The story of high mobility group protein B1 (HMGB1) in cancer is complicated and the function of HMGB1 in different cancers is uncertain." (PMID 26393575, 2015).
cancer (continued). "It is increasingly expressed when potential ligands such as HMGB1 or inflammatory mediators are abundantly expressed, e.g., in cardiovascular disease, diabetes or cancer." (PMID 26854151, 2015). "Next, to examine HMGB1 release, the cancer cell lines were treated with D10 doses of X-rays or carbon-ion beams, and the concentration of HMGB1 in the culture supernatant was measured." (PMID 25755254, 2015). "The present study is the first to demonstrate that human cancer cells irradiated with carbon-ion beams release HMGB1." (PMID 25755254, 2015). "High mobility group box 1 (HMGB1) is a nuclear protein, and is released when cancer tissues are destroyed by chemotherapy and radiation." (PMID 26690480, 2015). "Recently, HMGB1 has been shown to play an important role in cancer biology, including angiogenesis, apoptosis, growth signals, tissue invasion, and metastasis." (PMID 25622595, 2015). "Here, we examined the ability of carbon-ion beams and X-rays to induce the in vitro release of HMGB1 from human cancer cell lines originating from different organs." (PMID 25755254, 2015). "This review provides an in-depth look into the concepts and mechanisms underlying CALR exposure, activation of the Toll-like receptor 3/IFN/CXCL10 axis, and the release of ATP and HMGB1 from dying cancer cells." (PMID 26486085, 2015). "Clinical studies assessing the prognostic and predictive value of HMGB1 release and extracellular HMGB1 signaling in cancer patients." (PMID 26300886, 2015). "High serum HMGB1 levels in cancer patients and predominant cytoplasmic localization indicate that HMGB1 can be actively released into the circulation." (PMID 25652880, 2015). "HMGB1 can be extracellularly released by activated macrophages and necrotic cells, while many types of cancer cells can actively secrete HMGB1 5–7 or passively release HMGB1 in the process of dying 8,9." (PMID 26099505, 2015). "HMGB1 acts as a growth factor for cancer cells, it activates MAPK or PI3K/AKT signaling and enhances proliferation via RAGE receptor activation." (PMID 25652880, 2015). "The present study examined the levels of HMGB1 in the culture supernatants of human cancer cell lines treated with X-rays or carbon-ion beams." (PMID 25755254, 2015). "Taken together, both carbon-ion beams and X-rays induced the release of HMGB1 from different human cancer cell lines, and both types of radiation were equally effective at inducing HMGB1 release when given at iso-survival doses." (PMID 25755254, 2015). "HMGB1 released from apoptotic cell death is an important mediator of immunogenic cell death in cancer therapy by TLR4." (PMID 25904867, 2015). "As to the underlying signaling pathways, HMGB1 receptors in HCC include RAGE, TLRs and TREM-1, though there are a number of receptors of HMGB1 in other cancers." (PMID 26393575, 2015). "Several studies have reported the release of HMGB1 from cancer cells treated with ionizing irradiation or chemotherapeutic agents." (PMID 25755254, 2015). "Chemotherapeutic drugs are also known to induce HMGB1 up-regulation and impart drug resistance by inducing autophagy in different cancers." (PMID 26689911, 2015). "HMGB1 release is observed in macrophages, fibroblasts, and cancer cells during autophagy and autophagic cell death." (PMID 25904867, 2015). "Positive HMGB1 immunoreactivity was detected in 36/37 (97.3%) cancer cases, 24/25 (96%) CIN3 cases, 9/26 (34.6%) CIN1-2 cases and 0/12 (0%) control cases." (PMID 24837834, 2014). "When these cancer cells die after cytotoxic treatment, extracellular HMGB1 is detected in proportion to the levels of intracellular HMGB1." (PMID 25512109, 2014). "Dead cancer-CM, (shown to increase the level of extracellular HMGB1) also increased the survival of MDA-MB-231 cells during subsequent Dox treatment and this effect was reversed by an HMGB1 neutralizing antibody (**p-value = 0.006)." (PMID 25512109, 2014).